FOXM1 (forkhead box M1)
Diseases named in the same sentence as FOXM1 in open-access papers (continued):
Sharing a sentence is not in itself a finding about the gene and the disease.
cancer (continued). "As an important member of the FOXO family, Forkhead box M1 (FoxM1) affects cancer cell biological behaviors by manipulating the transcription of its target genes." (PMID 36301031, 2022). "Overexpression of FoxM1 promotes cell-cycle progression, leading to tumorigenesis and cancer progression." (PMID 35884976, 2022). "Overexpression of FOXM1 has been detected in a broad range of cancer types, including PDAC, contributing to all hallmarks of cancer." (PMID 35241126, 2022). "We found that tumors from both cancer cells lines treated with FOXM1-PROTAC were significantly smaller than those in the other two groups." (PMID 36171633, 2022). "During recent years, novel functions for FOXM1 have been identified in cancer cells beyond the simple acceleration of G2–M phase progression." (PMID 36481766, 2022). "It was also reported that RAS plays a critical role in FOXM1 induction in cancer cells by ROS involvement." (PMID 35241126, 2022). "In summary, our current findings exhibited that Artemisinin commendably repressed FoxM1 at its transcriptional level and curbed its downstream trans-activation ability, thus delaying cancer cell proliferation, relegating tumor growth and increasing apoptosis." (PMID 34900697, 2021). "While these agents can have potent anti-cancer effects, their link to FOXM1 is tenuous due to their pleiotropic effects." (PMID 34205406, 2021). "Among them, we found FOXM1, which is a transcription factor with a crucial, central role in cancer development." (PMID 33479222, 2021). "A recent study in 18,000 cancer cases involving 39 human malignancies showed FOXM1 regulatory network is an important predictor of poor prognosis." (PMID 34654353, 2021). "The results showed that FOXM1 was highly expressed in clinical cancer tissues, berberine treatment decreased significantly." (PMID 35173608, 2021). "This work demonstrates that hsa_circ_0042823 accelerates cancer progression by regulating miR-877-5p/FOXM1 axis in LSCC." (PMID 34124974, 2021). "Both the levels of CASC8 and the levels of FOXM1 were higher in the cancer tissues than in the adjacent normal tissues." (PMID 33391435, 2021). "Sensitization to antitumor drugs is the most well-characterized effect of FOXM1 downregulation in cancer cells." (PMID 34262016, 2021). "Meanwhile, the FoxM1/AKR1C1 axis in human cancers was the potential target of avasimibe which successfully retarded cell proliferation and tumor growth of CCA." (PMID 34127944, 2021). "FOXM1 regulates the expression of a multitude of genes that promote cancer, including those that increase the growth, survival, and metastatic spread of cancer cells." (PMID 34205406, 2021). "A study found that the upregulation of TF FoxM1 mediated the acquisition of cancer stem-like cell characteristics in NSSLC H460 cells with analysis of stemness markers (CD133, ALDH1, and CD44)." (PMID 34745015, 2021). "The FOXM1 field and publications have increased steadily since the year 2000, with a large proportion of studies focused on cancer." (PMID 34205406, 2021). "Exploring more molecular events regulated by FoxM1 will help us to further develop the potential cancer treatment strategy." (PMID 33526768, 2021). "Through direct and indirect downstream regulation of a broad spectrum of genes, FOXM1 plays an important role in proliferation, cell cycle control, DNA repair and thus in tumorigenesis, cancer progression and tumor growth." (PMID 33668819, 2021). "FOXM1 is designated as a proto-oncogene in most cancers, as it exclusively expressed in dividing cells and is involved in angiogenesis, cell migration and epithelial-to–mesenchymal transition." (PMID 34885040, 2021). "In PRC2+-CGI promoters, several known cancer-type-specific TFs were observed, such as FOXM1 in BasalBRCA39 and GATA3 in LumBRCA40; nevertheless, most TFs have not been previously reported in their corresponding cancer types." (PMID 33931649, 2021).
cancer (continued). "At the molecular level, Otub1 stabilizes several oncoproteins such as Snail, and FOXM1 as a deubiquitinase that result in cancer cell proliferation and survival." (PMID 33627137, 2021). "In vitro and in vivo studies confirm the positive feedback loop between DKK1 and FOXM1 promotes cancer cell proliferation, and our clinical data also indicates that PDAC and ESCC cases that simultaneously expressed DKK1 and FOXM1 show poor clinical prognosis." (PMID 34117362, 2021). "Considering EMT as a pivotal feature of cancer cells that render them with the dexterity to metastasize, we sought to explore the role of FoxM1 silencing in curbing this phenomenon in the resistant HCC cells." (PMID 34900697, 2021). "ALKBH5 also functions as an m6A demethylase, and increases the expression of its key target, FOXM1 (forkhead box M1), to promote the development of cancers by reducing m6A abundance on target mRNA transcripts (especially at the 3′ UTR)." (PMID 33692753, 2021). "In conclusion, our findings demonstrated that FDI-6 suppressed cancer cell proliferation, migration, and invasion via the downregulation of FOXM1 and its downstream targets." (PMID 34206484, 2021). "FOXM1 overexpression has been observed in many cancers and actively participates in tumor development by stimulating proliferation." (PMID 34117362, 2021). "Our observations showed that, once inside the cancer cells, Artemisinin-mediated blockage of FoxM1 trans-activation results in downregulation of major transcriptional targets of FoxM1, such as Plk1, cyclinB1, Skp2 and Aurora B kinase." (PMID 34900697, 2021). "FOXM1, a transcription factor upregulated in several cancer types, plays a key role in cell cycle progression, stemness and tumorigenesis." (PMID 34565361, 2021). "The observation further corroborates earlier studies that advocate FoxM1 deletion to drastically inhibit cancer cell invasion and metastasis." (PMID 34900697, 2021). "Forkhead box M1 (FOXM1), an oncogenic transcription factor associated with aggressiveness and highly expressed in many cancers, is an emerging therapeutic target." (PMID 34944900, 2021). "FOXM1 is reported to be associated with cancer proliferation, angiogenesis, EMT, migration, metastasis, and stemness in many types of cancer." (PMID 33868269, 2021). "Subsequent studies confirmed these observations in other cancers such as meningiomas and pancreatic tumors, suggesting that the nuclear shuttling of β-catenin by FOXM1 is a common pathomechanism in cancer." (PMID 34298659, 2021). "Meanwhile, inhibition of FOXM1 in cancer cells represses cell proliferation, EMT, migration, metastasis, angiogenesis, and drug resistance." (PMID 33937262, 2021). "Elevated FOXM1 expression is observed in a variety of human cancers, and inhibition of FOXM1 significantly suppresses the malignant phenotype of cancer cells." (PMID 34584067, 2021). "In cancer biology, FOXM1 is an important oncogene which is involved in tumor initiation, invasion, metastasis, and angiogenesis." (PMID 34335925, 2021). "Forkhead Box M1 (FoxM1) is a member of Forkhead transcription factors family, working as an oncogene in human malignant tumors." (PMID 34127944, 2021). "In this paper, we identified a novel chemical compound STL that suppresses FOXM1 activity in a variety of human cancer cell lines." (PMID 34262016, 2021). "FOXM1 is a transcription factor with important roles in cancer cell proliferation, migration, and invasion." (PMID 34740322, 2021). "We then discuss the evidence for and the manner by which FOXM1 expression promotes aggressive cancer biology." (PMID 34205406, 2021). "Heat shock protein 70 (HSP70) binds FOXM1, which inhibits mRNA and protein expression, and as such acts as a cancer suppressor gene." (PMID 34150631, 2021). "Our mechanistic study showed that FoxM1 transcriptionally activates STMN1 in cancer cells using the promoter reporter assay, ChIP-qPCR and bioinformatics analysis in ENCODE ChIP-seq database." (PMID 33526768, 2021).
cancer (continued). "The overexpression of FOXM1 in tumors of various cancers correlates with late stage, high proliferation rate, and poor prognosis." (PMID 34768915, 2021). "Our previous studies demonstrated that HGK can inhibit the expression of FOXM1 and Class I HDACs to suppress the growth of cancer cells." (PMID 34575923, 2021). "The expression of Foxm1 in differentiated adult tissue is low, and increases in FOXM1 expression are correlated with the initiation of cancer formation and tumor initiation." (PMID 34680943, 2021). "Most remarkably, a pan-cancer meta-analysis of the transcriptomes of ~18,000 human tumors identified FOXM1 expression as the top single gene predictor of poor prognosis in cancer." (PMID 34205406, 2021). "The apoptosis induced by siomycin A correlates with the suppression of FoxM1 expression, while overexpression of FoxM1 partially protected cancer cells from siomycin-mediated death." (PMID 33928382, 2021). "Collectively, these results demonstrated that STMN1 contributes to the FoxM1-induced proliferation and tumorigenesis of cancer cells in vitro and in vivo." (PMID 33526768, 2021). "To investigate the effect of FoxM1 and STMN1 on cancer progression, we performed survival analysis of all solid tumors from TCGA database according to FoxM1 and STMN1 expression." (PMID 33526768, 2021). "The data indicated that high levels of FoxM1 and STMN1 are closely associated with poor prognosis in cancers, thus shedding light on the prognostic value of combined utilization of FoxM1 and STMN1." (PMID 33526768, 2021). "While several early cancer investigations focused on FOXM1b, our recent studies of the TCGA database and human HGSC tissues revealed that FOXM1c is the highest expressed FOXM1 isoform in both pan-cancer and HGSC." (PMID 34205406, 2021). "In this article, this study focused on FOXM1B, which is also called FOXM1, which is different from other FOXM1 isomers in that it mainly regulates the growth, migration, and angiogenesis of cancer cells." (PMID 34654353, 2021). "Forkhead box protein M1 (FOXM1) is a transcription factor with multiple functions in several cancer and stem cells." (PMID 33572108, 2021). "So far many studies have revealed that microRNAs (miRNAs) are involved in the regulation of FOXM1 expression in cancer development." (PMID 33867818, 2021). "Although the role of B-Myb and FoxM1 upregulation in cancer progression is not fully understood, high expression of these factors can contribute to abnormal mitosis and chromosomal instability." (PMID 33747961, 2021). "FOXM1 is an oncogene involved in cancer progression, and its transcriptional targets directly control the cell cycle." (PMID 33660397, 2021). "Chromosome 12p13.33, where FOXM1 resides, shows copy number gains and amplifications in many human cancers, and studies indicate that this somatic copy number alteration (SCNA) can occur early in cancer development." (PMID 34205406, 2021). "Several mechanisms have been proposed to explain the activity of FOXM1 in cancer progression, including the activation of this factor by several oncogenic protein and signaling pathways, such as Ras and MAPK/Erk." (PMID 33799965, 2021). "Taken together, we revealed a generally transcriptional regulation of FoxM1 on the expression of STMN1 in cancers." (PMID 33526768, 2021). "Indeed, FOXM1 overexpression was detected in a variety of human cancers and is associated with poor clinical prognosis; it drives the expression of critical genes involved in the regulation of different cancer hallmarks including high proliferation, invasion, drug resistance, and angiogenesis." (PMID 33479222, 2021). "Different therapeutic approaches have been used to counteract the increase in FOXM1 in cancers, including targeting of ubiquitin-specific peptidase 5 (USP5)." (PMID 33804240, 2021).
cancer (continued). "The present study reveals that FOXM1 acts as a transcription factor for DKK1 in cancer cells and that the DKK1-FOXM1 signaling axis creates a positive feedback loop for cancer cell proliferation." (PMID 34117362, 2021). "A previous study demonstrated that FOXM1 is activated by an inflammatory microenvironment and that an increase in FOXM1 expression promotes cancer cell proliferation and resistance to apoptosis." (PMID 34740322, 2021). "FOXM1 has been widely involved in cancer progression and several molecules targeting FOXM1 pathway are currently under investigation." (PMID 34070214, 2021). "FOXM1 is overexpressed in many types of cancer and contributes to all cancer hallmarks, including increased proliferation, reduced apoptosis, tumor metastasis, and drug resistance." (PMID 34298659, 2021). "FOXM1 has been reported to be involved in various tumor processes, including cancer growth and aggression, cancer differentiation, stem cell phenotype, and EMT." (PMID 33428593, 2021). "These miRNAs target and downregulate FOXM1, thereby leading to the inhibition of cancer cell growth and metastasis." (PMID 33867818, 2021). "We expected that STL, being a FOXM1 inhibitor, should decrease drug resistance in human cancer cells when combined with standard chemotherapy drugs." (PMID 34262016, 2021). "As a master regulator of the cell cycle, the transcription factor FOXM1 is required for cell proliferation of normal cells, and it is an important factor in various types of cancer." (PMID 33953844, 2021). "Foxm1, a transcription regulator, is located to the nucleus and highly expressed in proliferating normal cells and various cancer cells." (PMID 34539442, 2021). "FOXM1 appears to be a master regulator of antioxidants, and its downregulation resulted in lower radiation sensitivity of cancer stem cells." (PMID 33867999, 2021). "As a result, the activities of the two cyclin complexes are dramatically reduced in FOXM1-depleted human cancer cells and MEFs." (PMID 34680943, 2021). "It has been recognized as a major predictor (actually indiscriminately referred to as FOXM1) of adverse outcomes in cancer by gene landscape analysis." (PMID 33314660, 2021). "It induced the downregulation of FOXM1 downstream target genes in cancer cells with a high FOXM1 expression." (PMID 34206484, 2021). "We additionally discuss the evidence for FOXM1 as a cancer biomarker, describe the rationale for FOXM1 as a cancer therapeutic target, and provide an overview of therapeutic strategies used to target FOXM1 for cancer treatment." (PMID 34205406, 2021). "We believe that both inhibition of FOXM1 and reduction in the level of FOXM1 in the cancer cells by these inhibitors contribute to their suppression of FOXM1 activity." (PMID 34944900, 2021). "The overexpression also caused a decrease in expression of cancer-promoting factors EZH2, DNMT1, FOXM1, EGFR, PCNA, AURKA, YAP1, and CDH2." (PMID 34595169, 2021). "FOXM1, a transcription factor, which elevated expression, was observed in various cancers, contributed to invasion and metastasis." (PMID 33673178, 2021). "We found that in HCC, UBE2S is upregulated by FOXM1, which is a transcription factor of the Forkhead box (Fox) protein superfamily, participating in the oncogenesis of many cancers." (PMID 34785642, 2021). "The abnormal expression of FOXM1 is closely related to the occurrence and development of various human malignant tumors." (PMID 33502747, 2021). "The transcription factor FOXM1 coordinates the expression of cell cycle-related genes and plays a pivotal role in tumorigenesis and cancer progression." (PMID 34621746, 2021). "The forkhead/winged helix domain transcription factor FOXM1 promotes cancer by transactivating genes with oncogenic potential." (PMID 33890574, 2021). "Previous studies have reported that knocking down FOXM1 sensitized cancer cells to apoptosis and also improved the efficiency of other treatments, such as irradiation or chemotherapeutic agents." (PMID 34206484, 2021).
cancer (continued). "This apparent contradiction to previous studies 37 is likely explained by the fact that the effectiveness of FOXM1 or CDK4/6 targeting is conditioned by the set of molecular alterations present in cancer cells." (PMID 34646365, 2021). "Other FOXM1 inhibitors, such as Siomycin A and thiostrepton, have been reported to induced apoptosis in cancer cells." (PMID 34206484, 2021). "In agreement, we more recently showed that FOXM1 copy number correlates with FOXM1 mRNA and protein expression in pan-cancer." (PMID 34205406, 2021). "Given that FOXM1 is an established oncogenic transcription factor which is upregulated in a variety of human cancers, we focused on characterizing the mechanism, whereby MGAT4EP/FOXA1 axis regulates its expression." (PMID 34425866, 2021). "The FOXM1 transcription factor is an oncoprotein and a top biomarker of poor prognosis in human cancer." (PMID 33890574, 2021). "Forkhead/wing helix domain transcription factor FOXM1, as an oncoprotein, affected the occurrence and development of cancer through trans activation of related oncogenes." (PMID 35173608, 2021). "In conclusion, we demonstrated that a general regulatory FoxM1–STMN1 axis promotes cell proliferation and tumorigenesis in FoxM1-driven cancers in vitro and in vivo." (PMID 33526768, 2021). "In this study, we aimed to explore FOXM1-regulated downstream miRNAs through analyzing the TCGA (The Cancer Genome Atlas) database and identified miR-552 as a new transcriptional target of FOXM1." (PMID 33867818, 2021). "Forkhead box protein M1 (FOXM1) is a pivotal regulator of G2/M cell cycle progression in many types of cancer." (PMID 34335925, 2021). "Mammalian transcription factor FOXM1, one of the members of the Forkhead family proteins, plays crucial roles in tumorigenesis in human cancers." (PMID 34435140, 2021). "It was worth noting that FOXM1 had been reported as the primary gene expression biomarker with poor prognosis in Pan-cancer analysis, which includes >18,000 tumors from 39 different malignancies." (PMID 35173608, 2021). "Previously, this in silico analysis strategy successfully identified the known FOXM1-mediated pathway, such as the cell cycle, in various cancer cell lines." (PMID 34067336, 2021). "It has also been reported that FOXM1 was overexpressed in a variety of human cancers and that the oncogenic potential of this gene is based on its ability to reactivate target genes involved in different stages of cancer development." (PMID 33912448, 2021). "c-Myc is known to transcriptionally activate FOXM1 in several cancers and, notably, exhibits copy number gains in >65% of HGSC cases." (PMID 34205406, 2021). "Repression of FOXM1 has been reported to induce the death of cancer cells by inhibiting DNA damage repair and cell cycle progression." (PMID 34880209, 2021). "FoxM1 is reported frequently overexpressed in many kinds of cancer types and contributing to promote cell cycle and leads to excessive cell growth." (PMID 33526768, 2021). "There is also evidence for a possible role of FOXM1 in self-renewal and proliferation of cancer stem cells (CSCs) and overexpression of FOXM1 led to an increased self-renewal capacity of human PDA cells in vitro, which correlated with an enhanced CSC marker." (PMID 33804240, 2021). "In fact, shRNA-mediated depletion of Aurora-A led to reduced cellular proliferation and colony formation in both N-Myc- and FOXM1-addicted cancer cells." (PMID 33981003, 2021). "FOXM1 expression predicts for adverse outcome in a range of cancers and is highly expressed in AML where it is required for proliferation, in keeping with its binding to cell cycle gene homology regions (CHR) via its interaction with the MuvB complex." (PMID 34711181, 2021).